G6PD (glucose-6-phosphate dehydrogenase)
Diseases named in the same sentence as G6PD in open-access papers (continued):
Sharing a sentence is not in itself a finding about the gene and the disease.
gastric cancer (continued). "As displayed by IHC staining, the brown color demonstrates the G6PD-positive IHC staining and the staining density and staining intensity were lower in gastric cancer tissues of sh-G6PD group than that in normal gastric cancer tissues." (PMID 33514309, 2021). "This is corroborated by the findings that both PFKFB3 and G6PD are overexpressed in patients with gastric cancer, and promoted the proliferation and migration of gastric cancer cells." (PMID 31591390, 2019). "This suggests that both PFKFB3 and G6PD are required for proliferation when Rev-erbα was reduced in human gastric cancer cells." (PMID 31591390, 2019). "We found that mutation of Rev-erbα DBD domain increased the mRNA slevels of PFKFB3 and G6PD in human gastric cancer cell." (PMID 31591390, 2019). "Pharmacological inhibition of glycolysis and the PPP using corresponding PFKFB3 and G6PD inhibitors attenuated Rev-erbα knockdown-induced proliferation in gastric cancer cells." (PMID 31591390, 2019). "Both PFKFB3 and G6PD were overexpressed in patients with gastric cancer, and positively correlated with the TMN stages." (PMID 31591390, 2019). "Utilizing clinical human samples, we found that the protein abundance of PFKFB3 and G6PD was increased in patients with gastric cancer." (PMID 31591390, 2019). "The elevated G6PD activities were observed in various human cancers, such as renal cell carcinoma, bladder cancer, as well as gastric cancer." (PMID 26607846, 2015). "Considering that the model showed an AUC of 0.70 with moderate sensitivity and specificity, the result suggests a potential role of serum G6PD activity as a biomarker for gastric cancer stage, but the predictive performance is limited for immediate clinical application." (PMID 41374996, 2025). "This study demonstrates that serum G6PD activity may serve as a valuable biomarker for predicting the stage of gastric cancer." (PMID 41374996, 2025). "Moreover, RORα expression inversely correlates with G6PD and PFKFB3, and low RORα combined with high G6PD or PFKFB3 predicts poor survival in gastric cancer, indicating RORα as a potential biomarker and therapeutic target." (PMID 41425709, 2025). "Moreover, for the diagnosis of gastric cancer, miRNAs and CTCs showed higher AUC, sensitivity, and specificity compared to serum G6PD levels." (PMID 41374996, 2025). "In addition, G6PD promotes gastric cancer cell proliferation and metastasis through mechanisms mediated by NF-kB and hexokinase 2 (HK2)." (PMID 41374996, 2025). "Therefore, this study aimed to investigate the potential of serum G6PD activity as a biomarker for predicting the stage of gastric cancer." (PMID 41374996, 2025). "Therefore, G6PD participates in gastric cancer progression through multiple mechanisms, and it is indispensable for the proliferation and migration of gastric cancer cell." (PMID 41374996, 2025). "The G6PD activity test could aid not only in monitoring stage I–II gastric cancer patients during follow-up for potential recurrence as stage III–IV disease but also in assisting the initial clinical staging at diagnosis." (PMID 41374996, 2025). "Furthermore, given that the G6PD activity assay is portable, user-friendly, and yields rapid results, it is well suited for short-term follow-up assessments for gastric cancer patients." (PMID 41374996, 2025). "Furthermore, an increase in miR-1-3p expression leads to the downregulation of the G6PD target gene with a decrease in cell proliferation and aerobic glycolysis but increases cell apoptosis in gastric cancer cells." (PMID 39457531, 2024). "Interestingly, miR-1-3p can target glucose-6-phosphate dehydrogenase (G6PD) to affect the Warburg effect (aerobic glycolysis) of gastric cancer cells." (PMID 37907984, 2023). "G6PD expression within gastric cancer tissue samples and cells was examined." (PMID 33514309, 2021). "As G6PD is highly expressed in gastric cancer tissues, it is speculated that it plays a key role in regulating cytokine production." (PMID 33718248, 2021).
gastric cancer (continued). "There are three miRNAs (hsa-miR-1-3p, hsa-miR-613 and hsa-miR-206) targeted G6PD in gastric cancer." (PMID 33514309, 2021). "All these results proved that overexpressed G6PD was observed in gastric cancer tissues and cells, which may in correlation with gastric cancer patient’s poor survival rate." (PMID 33514309, 2021). "G6PD expression level was observably high-expressed in gastric cancer tissues and cells." (PMID 33514309, 2021). "The abnormal high-expression of G6PD suggests that it may serve as a tumor promoter against gastric cancer." (PMID 33514309, 2021). "Firstly, there could be other miRNAs sponged by LINC00242 or G6PD and involved in gastric cancer aerobic glycolysis, as well as other functional gene targets of miR-1-3p." (PMID 33514309, 2021). "Moreover, the results of H&E staining in gastric cancer tissues demonstrated that tumor tissues in sh-NC group showed obvious necrosis, whereas silencing of G6PD improved the necrosis in tumor." (PMID 33514309, 2021). "Besides, a growing body of research manifested that G6PD participate in the crucial development progresses of multiple types of human tumor, including gastric cancer." (PMID 33514309, 2021). "In addition, the analysis of TCGA data revealed the up-regulation of PGK1 and G6PD in common cancers such as colon, lung and gastric cancers." (PMID 32028979, 2020). "It remains elusive whether Rev-erbα inhibits PFKFB3 and G6PD gene expression using similar mechanisms in human gastric cancer cells." (PMID 31591390, 2019). "This was due to increased expression of PFKFB3 and G6PD in human gastric cancer cells." (PMID 31591390, 2019). "We found that Rev-erbα could be recruited on the promoters of PFKFB3, an isoform of PFK, and G6PD genes, and directly inhibited their gene transcription in human gastric cancer cells." (PMID 31591390, 2019). "Overall, these results suggest that G6PD overexpression may represent an independent predictor of poor prognosis for patients with gastric cancer." (PMID 28553614, 2017). "In gastric cancer (GC), LINC00242 competitively combined miR-1-3p, thus relieving miR-1-3p-mediated suppression on G6PD and promoting aerobic glycolysis and GC progression." (PMID 39859324, 2025). "Hence, further thorough-paced investigation on regulator modulating G6PD expression and Warburg effect advancement in gastric cancer might define feasible targets for gastric cancer therapy." (PMID 33514309, 2021). "We finally verified the mRNA expression of EZH2, G6PD, LGALS3 and PSMD14 by qRT-PCR in clinical gastric cancer tissue samples." (PMID 37853322, 2023). "LNC00242 was high-expressed in gastric cancer (GC) tissue regulated by LINC00242/miR-1-3p/G6PD axis, and it may be a promising biomarker of GC." (PMID 35223846, 2022). "Along with the data on ECAR, lactate, and glucose consumption, Rev-erbα suppresses glycolytic flux and the PPP in gastric cancer cells by inhibiting PFKFB3 and G6PD gene expression." (PMID 31591390, 2019). "This was corroborated by our findings that pharmacological inhibition of glycolysis and the PPP reduced proliferation in gastric cancer cells, whereas overexpression of PFKFB3 and G6PD augmented proliferation in these cells." (PMID 31591390, 2019). "To extrapolate the in vitro findings into human samples, we determine the expression of PFKFB3 and G6PD as well as the metabolites, including lactate, pyruvate and NADPH in patients with gastric cancer." (PMID 31591390, 2019). "In summary, we demonstrated for the first time that Rev-erbα was recruited to promoters of PFKFB3 and G6PD genes, thereby inhibiting glycolytic flux and the PPP, and subsequent proliferation in in vitro human gastric cancer cells." (PMID 31591390, 2019). "Concerning the molecular mechanism, LINC00242 competitively regulated miR-1-3p, therefore offsetting miR-1-3p-mediated suppression on G6PD, indicating that LINC00242 modulates gastric cancer cell aerobic glycolysis and proliferation through miR-1-3p and G6PD signaling." (PMID 33514309, 2021).
gastric cancer (continued). "In consideration of miRNA also exerts a crucial role of aerobic glycolysis in gastric cancer, the present study screened that miR-1-3p could straight targeted bind to LINC00242 and G6PD 3′UTR, respectively." (PMID 33514309, 2021). "Although Rev-erbα inhibited PFKFB3 and G6PD gene expression, it is unclear whether PFKFB3 and G6PD mediate the effect of Rev-erbα on proliferation of human gastric cancer cells." (PMID 31591390, 2019). "Forth, several confounders that could affect G6PD levels and gastric cancer progression were not fully considered." (PMID 41374996, 2025).
prostate carcinoma (23 papers, 2014 to 2025). A carcinoma that arises from epithelial cells of the prostate gland. "Numerous studies biologically demonstrated the association between G6PD activity and bone metastasis of prostate cancer." (PMID 41514554, 2025). "G6PD activity in prostate cancer tissues positively correlates with the Gleason grade, which is commonly associated with prostate cancer aggressiveness and progression." (PMID 41514554, 2025). "G6PD activity was significantly associated with bone metastasis in prostate cancer, with an OR of 1.08." (PMID 41514554, 2025). "It has been reported that high G6PD expression increases doxorubicin resistance in triple negative breast cancer and is associated with a reduction in progression-free survival in prostate cancer bone metastasis." (PMID 37242427, 2023). "Genetic and pharmacologic manipulation demonstrates that G6PD inhibition reduces prostate cancer growth and migration, associated with changes in cellular redox state and increased chemosensitivity." (PMID 35213227, 2022). "Overall, the loss of G6PD expression in prostate cancer cells resulted in a reduction in tumor growth and survival within bone." (PMID 35213227, 2022). "This bone marrow stromal cell–G6PD axis regulates the redox state of prostate cancer cells, with a loss of G6PD elevating ROS, decreasing antioxidants, and enhancing the chemosensitivity of prostate cancer cells." (PMID 35213227, 2022). "We suggest that serial monitoring of G6PD activity may help assess the risk of bone metastasis and enable early detection in patients with prostate cancer." (PMID 41514554, 2025). "To study whether G6PD was regulated by mTOR signaling in vivo, we performed immunohistochemical analysis of two different autochthonous in vivo models of prostate cancer caused by Pten loss-of-function." (PMID 24861463, 2014). "In this study, we explored the clinical relevance of G6PD activity in predicting bone metastasis among prostate cancer patients." (PMID 41514554, 2025). "Recent study suggests that AR signaling promotes prostate cancer cell growth by increasing G6PD expression and enhancing flux through pentose phosphate pathway via activation of the mTOR-SREBP1 axis." (PMID 41514554, 2025). "On the other hand, prostate-specific antigen (PSA), a widely used biomarker in prostate cancer management, has demonstrated a sensitivity of 0.85 and a specificity of 0.84, both of which are higher than those of G6PD activity." (PMID 41514554, 2025). "This study revealed clinical utility of G6PD activity as a biomarker for predicting bone metastasis in prostate cancer." (PMID 41514554, 2025). "G6PD expression in prostate cancer is tightly regulated by both intrinsic oncogenic signaling and extrinsic cues from the tumor microenvironment." (PMID 41514554, 2025). "Firstly, inhibition of G6PD in prostate cancer cells leads to decrease NADPH and RNA synthesis, along with increased reactive oxygen species (ROS) level." (PMID 41514554, 2025). "In prostate cancer, G6PD expression has been shown to increase with tumor progression, and metastatic prostate cancer exhibits higher level of G6PD expression compared to localized prostate cancer or benign prostatic tissue." (PMID 41514554, 2025). "G6PD is highly expressed in prostate cancer and is strongly correlated with bone metastasis and poor prognosis in patients." (PMID 40533802, 2025). "In the setting of bone metastasis, G6PD expression in prostate cancer cell is upregulated by cytokine secreted by cells within the bone and through androgen receptor (AR) signaling." (PMID 41514554, 2025). "This study aimed to evaluate the potential of G6PD activity level as a biomarker for predicting bone metastasis in patients with prostate cancer." (PMID 41514554, 2025). "Within the bone microenvironment, interleukin-6 (IL-6) secreted by bone marrow stromal cells has been shown to induce the upregulation of G6PD expression in prostate cancer cell." (PMID 41514554, 2025).
prostate carcinoma (continued). "Given its role in tumor progression and its regulation within the bone microenvironment, G6PD is a potential biomarker for predicting bone metastasis in prostate cancer." (PMID 41514554, 2025). "In animal models, G6PD expression increased with prostate cancer progression and remained elevated in castration-resistant prostate cancer." (PMID 41514554, 2025). "The aim of this study is to evaluate the potential of G6PD activity level as a biomarker for predicting bone metastasis in patients with prostate cancer." (PMID 41514554, 2025). "G6PD activity has the advantage of predicting bone metastasis of prostate cancer through a simple blood test." (PMID 41514554, 2025). "First, it is the first study to propose G6PD activity as a potential biomarker for predicting bone metastasis in prostate cancer." (PMID 41514554, 2025). "The suppression of G6PD has been observed to hinder the growth and migration of prostate cancer cells, highlighting its potential as a therapeutic target." (PMID 38893112, 2024). "Androgen receptor signalling reportedly promotes the PPP through mTOR-mediated up-regulation of G6PD in prostate cancer." (PMID 39025830, 2024). "It was found that a G6PD-knockout prostate cancer cell line showed significantly lower CSI, while a G6PD-overexpression multiple myeloma cell line showed higher CSI." (PMID 36765548, 2023). "Pharmacological blockade of G6PD using 6-AN significantly elevated ROS in LNCaP prostate cancer cells." (PMID 35213227, 2022). "Having identified that the bone microenvironment drives G6PD overexpression, we explored the function of G6PD in prostate cancer cells." (PMID 35213227, 2022). "Overexpression of G6PD resulted in a significant increase in prostate cancer proliferation and colony formation, with a significant reduction in E-cadherin indicating a more mesenchymal phenotype." (PMID 35213227, 2022). "RNA sequencing (RNA-seq) confirmed gene changes in prostate cancer cells with knockdown of G6PD that suggested a more epithelial, less invasive, and proliferative phenotype." (PMID 35213227, 2022). "Our analysis found that G6PD was significantly up-regulated in metastatic, including bone metastatic, prostate cancer samples compared to primary tumors." (PMID 35213227, 2022). "In summary, we demonstrate the metabolic plasticity of prostate cancer cells in the bone microenvironment, identifying the PPP and G6PD as metabolic targets for the treatment of prostate cancer bone metastasis." (PMID 35213227, 2022). "We show that pharmacological, genetic, and microenvironmental regulation of G6PD can alter the redox state of prostate cancer cells." (PMID 35213227, 2022). "In vitro, pharmacological inhibition of G6PD using 6-AN was found to significantly reduce proliferation; notably, the reduction in prostate cancer cell viability was greater when cells were cultured in the presence of bone marrow stromal cells." (PMID 35213227, 2022). "Our metabolomic and in silico analyses have identified the PPP and, more specifically, G6PD as elevated in the prostate cancer–bone microenvironment." (PMID 35213227, 2022). "More recently, G6PD levels have been found to be elevated in prostate cancer, with G6PD proposed as a mediator of AR signaling." (PMID 35213227, 2022). "G6PD levels control prostate cancer cell growth both in vitro and in vivo, with G6PD inhibition, either by genetic modulation or pharmacological inhibition, resulting in a reduction in growth and survival." (PMID 35213227, 2022). "We demonstrate that the PPP and in particular its rate-limiting enzyme G6PD are up-regulated in prostate cancer bone metastasis." (PMID 35213227, 2022). "To further investigate the increase in G6PD within the bone microenvironment, we took advantage of prostate cancer cell lines with low G6PD expression (LNCaP and C42B)." (PMID 35213227, 2022).